CSF1 (colony stimulating factor 1)
Diseases named in the same sentence as CSF1 in open-access papers (continued):
Sharing a sentence is not in itself a finding about the gene and the disease.
tumor (continued). "Surufatinib, a novel small-molecule inhibitor, exhibits a unique dual action by targeting both tumor angiogenesis (VEGFR1/2/3 and FGFR1) and immune evasion through the macrophage colony-stimulating factor 1 (CSF1) receptor." (PMID 38730642, 2024). "Recent discoveries have highlighted the substantial influence of CAFs and the CSF-1/CSF-1R axis on the TME, affecting both tumor progression and immune responses." (PMID 39457693, 2024). "In solid tumors, including TCC, macrophages are attracted to the tumor site through chemotactic molecules such as CCL2 (MCP-1) and CSF-1 (M-CSF)." (PMID 38338162, 2024). "The first group of studies revealed that the inhibition of the (CSF-1)/CSF-1R pathway, which triggers TAM recruitment into tumor and M2-polarization of the recruits, only pushes the TAMs to the M1-like phenotype, which also causes CD8+ Tc cell activation." (PMID 36902456, 2023). "Signals in the tumor milieu [IL -4, IL -6, IL -10, prostaglandin E2 (PGE2), colony-stimulating factor 1 (CSF-1), and TGF-β] polarize macrophages into alternative, pro-inflammatory, pro-angiogenic, and immunosuppressive, protumoral M2-like cells." (PMID 36260158, 2023). "Besides directly suppressing tumor growth via the inhibition of Brd4 and c-MYC transcription, NHWD-870 also suppressed the proliferation of tumor-associated macrophages (TAMs) through reducing the expression and secretion of the macrophage colony stimulating factor CSF1 by tumor cells." (PMID 37049806, 2023). "Gonadotroph tumor cells polarize macrophages to the M2 phenotype, while somatotroph and gonadotroph tumor cells can recruit macrophages via CCL5 and colony-stimulating factor-1 (CSF-1)." (PMID 37958702, 2023). "Other strategies targeting the CSF1/CSFR1 axis like CSF1R blockade by PLX3397, an inhibitor for CSF1R tyrosine kinase, have shown to inhibit tumour progression in mouse models of HCC by shifting the polarization of TAMs." (PMID 37894344, 2023). "So, before targeting the macrophage or CSF1/CSF1R pathway, one must consider the tumor subtype and its genetic drivers." (PMID 37279073, 2023). "In TME, CAFs can regulate tumor progression and immunity by producing growth factors, cytokines, and chemokines, including CCL2, CCL5, CSF1, CXCL5, CXCL9, CXCL10, and CCL5." (PMID 37206921, 2023). "In independent cohorts, TRAIL-receptor expression was higher in tumor tissue and seen in malignant cells, with TRAIL and CSF1 expressed by intra- and peritumoral immune cells." (PMID 37404757, 2023). "This study demonstrates CSF1/CSF1R signaling inhibition enhances the expansion of neoepitope-specific T cells and promotes an immune-permissive tumor microenvironment." (PMID 37505292, 2023). "Therapies that block the CSF-1/CSF-1R axis and that, in general, chemokine-targeted therapies (antiCXCL12 or anti-CCL2) not only have the effect of acting directly on tumor growth and propagation but also target the TME formed by immune cells." (PMID 37958702, 2023). "In vitro, suppression of DHX9 expression led to the downregulation of CSF1, suggesting that DHX9 should be considered as another potential target for immunotherapy, which is related to the known tumor suppressive effect of the downregulation of CSF1." (PMID 38275375, 2023). "Due to the role of various chemokines (such as CCL2 and CCL5) and cytokines (for example, CSF1 and members of the VEGF family) at the tumor site, monocytes are recruited at the tumor site to form TAMs." (PMID 37111726, 2023). "Of interest, a mouse model of CRC animal treated with neutralizing antibodies against CXCL12 and CSF1 showed a strong increase in CD8+ T lymphocyte infiltration and reduction in tumor growth." (PMID 37175861, 2023). "Drugs targeting macrophage related markers such as CSF-1, IFN-γ, VEGF, chemokines, and cell surface antigens are being gradually put into trials, and are one of the future research focuses of tumor immunotherapy targeting macrophages." (PMID 37810971, 2023).
tumor (continued). "CSF1/CSF1R signaling axis had been proved induced macrophages to M2 polarization and promoted tumor growth and lung metastasis." (PMID 37065499, 2023). "The interaction pairs via SPP1, RARRES2, NECTIN3, LGALS9, and LAMB1 showed increased signaling in the autophagy-high tumor cells, while SEMA3C, PTN, ICAM1, GAS6, and CSF1 showed decreased signaling compared with those in the autophagy-low tumor cells." (PMID 36830707, 2023). "Diminishing angiogenesis and tumor growth by depleting TAMs with approaches including CSF1 inactivation, CSF1 receptor (CSF1R) antibodies, and clodronate liposomes has been shown in a variety of tumor types." (PMID 37426676, 2023). "The tumour-associated microglia and macrophages (TAMs) present in the GB tumour microenvironment release growth factors and cytokines, including EGF (Epidermal Growth Factor) and CSF-1, which can promote tumour proliferation, survival and invasion." (PMID 37803333, 2023). "Nerve-related macrophages accumulate in the nerves invaded by tumor cells along the gradient of CCL2 and CSF-1 recognized by CCR2 and CSF-1R receptors, respectively." (PMID 36900158, 2023). "In addition, inflammatory cells within the tumor microenvironment may contribute to the production of tumor-promoting molecules, such as growth factors, pro-angiogenic cytokines, and enzymes that can promote invasion (e.g., CSF-1, EGF, VEGF, and MMP-9)." (PMID 36672343, 2023). "The PLX3397 activates the immune response by inhibiting the CSF1/CSF1R pathway in TAMs, further enhancing CD8+ T cell infiltration and reversing tumor immunosuppression (macrophage polarization)." (PMID 36903458, 2023). "Prior research focusing on the targeting of the CSF1/CSF1R signaling axis had shown varied results, from promising data in preclinical models to limited anti-tumor effects later in clinical trials." (PMID 37505292, 2023). "Various recruitment signals have been recognized, including colony-stimulating factor-1 (CSF-1), monocyte chemoattractant protein-1 (MCP‐1), and stromal-derived factor (SDF)-1α derived from tumor cells and other cells in the TME." (PMID 37731483, 2023). "CSF-1 also stimulates macrophages to release EGF, thereby promoting proliferation and migration of tumour cells, whereas EGF stimulates secretion of CSF-1 in tumour cells, thus forming a positive feedback loop between tumour cells and macrophages." (PMID 38143746, 2023). "Moreover, YAP/TAZ mobilize myeloid-derived suppressor cells (MDSCs) and tumor-associated macrophages (TAMs) by upregulating various cytokines, including C-X-C motif chemokine 5 (CXCL5), C-C motif chemokine 2 (CCL2), macrophage colony-stimulating factor 1 (CSF1), and interleukin-6 (IL6)." (PMID 38067201, 2023). "M2-like TAMs, activated by IL-4, IL-13, IL-10, and M-CSF/CSF-1, can secrete cytokines such as TGF-β, VEGF, and EGF, which would further promote tumor pre-metastatic niche formation and angiogenesis around the niche." (PMID 37238210, 2023). "In disease states, tissue-resident macrophages and circulating inflammatory monocytes are recruited to the tumor periphery and develop into M0-TAMs under the recruitment of multiple chemokines (CCL2 and CCL5) and cytokines (CSF-1 and VEGF family members)." (PMID 37138860, 2023). "It was found that CSF-1/CSF-1R signaling inhibition can reduce TAM infiltration and enhance the CD8+/CD4+ T-cell ratio to kill tumor cells." (PMID 36816959, 2023). "CSF-1, TGF-β1, macrophage inhibitory cytokine 1 (MIC-1), osteopontin (OPN), and Periostin produced by GBM cells recruit and polarize macrophages to a tumor-supporting M2-like phenotype." (PMID 37731483, 2023). "Major initiators of tumor inflammation such as CCL2, CXCL1, CXCL2, CXCL11, CSF1, LTB, and TNFSF10 were found to increase in both cell lines, while inflammation suppressors like IL13and IL1RN were decreased." (PMID 36831395, 2023).
tumor (continued). "In solid tumor studies, including breast and lung cancers, TAMS promotes releasing tumor-derived CSF-1 and macrophage-derived EGF by invading tumor cells involving paracrine signaling circulation." (PMID 36999020, 2023). "Multiple clinical trials are ongoing to evaluate the effects of CSF-1/CSF-1R blockade on TAM populations and tumor control in many both solid tumors and hematologic cancers." (PMID 37114134, 2023). "The mechanism by which macrophages infiltrated the TME was through the increase in colony-stimulating factor (CSF1) and chemokine ligand 2 (CCL2) (both involved in macrophage recruitment) in post-treatment MYCN-amplified tumours." (PMID 37887559, 2023). "To further understand the potential tumor cell-centric mechanisms resulting from knocking out CSF1 expression in both the 4T1 and MC38 tumor models, we assessed the expression of 178 genes by real-time-PCR array." (PMID 37505292, 2023). "Sorafenib and sunitinib are among RTKIs that block angiogenesis and tumor growth via targeting the RAF/MEK/ERK signaling pathway, VEGFR-2, PDGFRB, and colony-stimulating factor-1 (CSF-1)." (PMID 36984763, 2023). "Rapid recruitment of circulating inflammatory monocytes to the site of tumor growth can be achieved by specific signaling molecules such as CCL2, CSF-1, mediators, and complement components (in particular C5)." (PMID 37138860, 2023). "Tumor cells attract the macrophage cells in metastatic sites by releasing VEGF, CSF-1, TGF-β, and TNF-α, and these macrophages increase the tumor invasion by remodeling collagen fibers." (PMID 38017494, 2023). "Whereas the anti-tumor effect in MC38 parental tumors was limited, we observed significant tumor growth inhibition in MC38 CSF1 knockout tumors following treatment with immune checkpoint blockade alone or in combination with neoepitope vaccine." (PMID 37505292, 2023). "In recent years, several preclinical and clinical trials have explored the combination of CSF1/CSF1R inhibitors with various immunotherapies, such as immune checkpoint blockade, chemotherapy, and radiotherapy in several tumor models." (PMID 37505292, 2023). "Overexpression of miR-125b inhibited TGCT growth by targeting CSF1 and CX3CL1, which are known tumour-derived chemokines involved in the recruitment of macrophages to the neoplastic sites." (PMID 36768818, 2023). "Evidence suggests that tumor derived chemokines and cytokines including CCL2, CSF1, ECM components and hypoxia are involved in the recruitment of monocytes/macrophages." (PMID 37656220, 2023). "Macrophages are recruited and educated by multiple factors in the TME, including colony-stimulating factor-1 (CSF1), GM-CSF, TGF-β, IL-1, IL-4, CCL2, CCL5, immune complexes, complement, histamine, tumor-derived non-coding RNAs." (PMID 38008741, 2023). "Tumor cells and stroma, which make up the hypoxic core of the tumor microenvironment, promote the production of VEGF, CCL2, CCL5, CSF-1, EMAP-II, endothelin-2, SEMA3A, oncostatin M, and eotaxin." (PMID 37056346, 2023). "Colony-stimulating factor-1 (CSF1) has been known to play a role in the differentiation and accumulation of macrophages at the tumor niche and has been known to stimulate the M2-type phenotype in the TME." (PMID 36769180, 2023). "Previous research has demonstrated that tumor cells synthesize CSF-1 to induce macrophage migration, and these macrophages can secrete EGF to stimulate tumor cell migration." (PMID 37359527, 2023). "Meanwhile, studies reported tumor and stromal cells in the tumor microenvironment release chemokines (for instance, CCL2 and CCL5) and cytokines (such as CSF-1 and VEGF), recruiting circulating monocytes, resulting in tumor-associated macrophages (TAMs)." (PMID 36421355, 2022). "First, hypoxia‐triggered release of chemoattractants (i.e., CCL2, CCL5, CXCL12, CSF‐1, and VEGF) from tumor cells and non‐tumor cells to enhance TAMs precursor monocytes recruitment." (PMID 37323705, 2022).
tumor (continued). "Tumors cells secrete CSF-1 to activate macrophages in secreting EGF and subsequently promote tumor growth." (PMID 36439180, 2022). "Hypoxia, the growth factors CSF1 and VEGF, and chemotactic factors in the tumor microenvironment all contribute to increased macrophage recruitment and infiltration into the tumor matrix and blood vessel margins." (PMID 35847885, 2022). "Chemoattractants secreted by macrophages that control their recruitment to the tumor site include chemokines, e.g., CCL2 or CCL5, and cytokines, e.g., CSF-1 and members of the VEGF family." (PMID 36077705, 2022). "Some studies have revealed that CSF1 produced by tumor cells can accelerate the accumulation of TAMs, and CSF1R signaling blockade can delay tumor progression and reduced metastasis by depleting TAMs." (PMID 35593325, 2022). "Monocytes/MP are attracted from blood, bone marrow, and spleen to the tumor site thanks to CCL2, CCL5, and CSF-1 produced by the tumors cells, fibroblasts, endothelial cells, and even by the TAM themselves." (PMID 35163420, 2022). "Resident and infiltrating TAMs are recruited to the growing tumor in response to a variety of tumor-secreted cytokines, including CCL2, GM-CSF, EGF, CXC3CL1, SDF-1, and CSF-1." (PMID 35885058, 2022). "Pharmacologic targeting of this axis mainly relies on anti-CSF1 or anti-CSF1R agents as well as on CSF1R tyrosine kinase inhibitors (TKIs) and has shown anti-tumor activity in several pre-clinical models." (PMID 36077813, 2022). "M-MDSCs and monocytes are mainly recruited by chemokines produced by tumor cells, including CCL2, CCL5, and CSF1." (PMID 35122833, 2022). "For example, TAb2 tumors expressed a higher level of CSF1, VEGF-C and VEGF-D, and TAb2 tumor cells drastically expanded F4/80+ TAMs from bone marrow precursors in a CSF1 and VEGF dependent manner." (PMID 36330485, 2022). "A high expression of CSF-1/CSF-1R and a high density of TAMs and CD3+ T-lymphocytes create an immunosuppressive tumour milieu that is related to tumoral immune escape through the inhibition of T lymphocytes and to BC progression." (PMID 36294305, 2022). "CSF1‐secreting malignant T cells can bind to CSF1R to induce the development and survival of TAMs, promoting tumor survival and suppressing host antitumor immunity." (PMID 35441741, 2022). "Inflammatory monocyte mobilization decreases patient survival, and targeting the CCL2/CCR2 or CSF1/CSF1R axis that allows targeting macrophages or myeloid cell lineages improves chemotherapeutic efficacy and anti-tumour T-cell response." (PMID 36077801, 2022). "Tumor cells release chemoattractant proteins that recruit GAMs, such as CCL2, colony stimulating factor-1 (CSF-1), granulocyte–macrophage colony stimulating factor, hepatocyte growth factor or scatter factor, stroma-derived factor 1 (SDF-1), and GDNF." (PMID 35448036, 2022). "Chemokines such as CSF1 and CCL2 secreted by tumor cells can recruit monocytes from peripheral circulating blood to the tumor microenvironment (TME), and then monocytes differentiate into macrophage." (PMID 36313679, 2022). "Although KLF6 and CSF1 are differentially regulated by UHRF1, their regulatory mechanisms are functionally orchestrated to help UHRF1 fulfill its tumor-promoting roles in the course of HCC progression." (PMID 35664070, 2022). "Tumor cells and macrophages can communicate with each other with a set of chemical signalling pathways, mainly EGF and CSF-1." (PMID 36439180, 2022). "CSF-1 engagement with its receptor CSF-1R promotes human monocyte differentiation into macrophages, resulting in increased level of TAMs in TME to promote tumor invasion, metastasis, and angiogenesis." (PMID 36419877, 2022). "To further investigate changes in the tumor microenvironment, we determined the levels of TAM‐produced cyto/chemokines Ccl2, Ifnγ, Cxcl10, Cxcl9, Csf1, Csf3, and Il‐6 in the peritoneal lavage." (PMID 36221913, 2022).
tumor (continued). "Hypoxia induces tumor cells and stroma to produce cytokines, such as CCL2 (C–C motif chemokine ligand 2), CXCL12 (C-X-C Motif Chemokine Ligand 12), CSF1 (Colony Stimulating Factor 1) and VEGF to recruit macrophages." (PMID 35361234, 2022). "In TMEM, TAMs can produce EGF (epidermal growth factor) and secrete chemokine CCL18, and tumor cells can also secrete chemokine CCL18 and produce cytokine CSF-1, all of which play important roles in the process of tumor cell invasion." (PMID 36131942, 2022). "Colony-stimulating factor-1 (CSF-1) and C−C chemokine ligands, such as CCL2, are crucial tumor-derived factors that mediate the crosstalk between monocytes and tumor cells and foster continuous recruitment and differentiation of monocytes in the TME." (PMID 36679900, 2022). "Targeting the CSF1/CSF1R axis either alone or in combination with checkpoint blockade, or adoptive T cell therapy has decreased tumor MDSCs and improved anti-tumor responses in multiple tumors." (PMID 35122833, 2022). "Moreover, tumor-associated macrophages contribute to MM-associated neovascularization via vasculogenic mimicry and indirectly via secretion of pro-angiogenic factors such as VEGF, IL-8, FGF-2, MMPs, cycloxygenase-2 (COX-2), and colony stimulating factor-1 (CSF-1)." (PMID 35692781, 2022). "Tumor cells also release many cytokines including CCL2, CXCL12 and CSF1 that attract TAMs to help tumor escape by producing IL-10 and also directly inhibiting CAR T-cells via PD-1-PD-L1 interaction." (PMID 36569859, 2022). "This study also found that PD-1/PD-L1 expression on TAMs and CTLA-4 expression on CD8+ T cells was increased in the presence of CSF-1/CSF-1R blockade, and the combination of PD-1 or CTLA-4 antagonists resulted in more significant tumor regression." (PMID 35874717, 2022). "Both the selective monocyte targeting chemotherapeutic agent, trabectedin, and colony-stimulating factor 1 (CSF1) inhibitor that targets TAM can inhibit the recruitment of macrophages to TME, resulting in reduced tumor growth and metastasis formation." (PMID 35743249, 2022). "It has been reported that immunomodulatory proteins and chemokines, including CSF-1, CCL2, FTH, FTL, and TGFβ, are highly enriched in exosomes produced by hypoxic tumor cells." (PMID 36224346, 2022). "Macropinocytosis can be induced in macrophages by stimuli other than CSF1, including lipopolysaccharide (LPS), the chemokine CXCL12 and the tumor promoter phorbol 12-myristate 13-acetate (PMA)." (PMID 35107133, 2022). "Factors, such as colony-stimulating factor 1 (CSF1) and CCL2, secreted by the TME recruit macrophages to the tumor, and activation of the effector YAP in the Hippo pathway underlies the recruitment of macrophages by tumor-initiating cells (TICs)." (PMID 35071016, 2021). "FL-FDC crosstalk supports tumor growth and, through CCL2 and colony stimulating factor-1 (CSF-1) secretion, promotes monocyte recruitment, differentiation, and polarization toward the M2-like phenotype." (PMID 35008305, 2021). "Monocytes are recruited to the tumor by various growth factors and cytokines such as CCL2, CCL5, and CSF1." (PMID 34209703, 2021). "Several chemokines such as macrophage colony-stimulating factor-1 (MCSF/CSF1) and monocyte chemotactic protein-1 (MCP1/CCL2) are known to contribute to the recruitment of TAMs to the tumor." (PMID 33544755, 2021). "Human cancer cell lines secrete cytokines able to impair macrophage anti-tumor properties, i.e., IL-10, TGF-β, and PGE2 stimulate myelopoiesis, producing granulocyte and macrophage growth factors, i.e., M-CSF (CSF-1), GM-CSF (CSF-2), and G-CSF (CSF-3)." (PMID 34680425, 2021). "Meanwhile, remaining TAMs are reprogrammed by CSF1/CSF1R blockade to support antigen presentation and bolster T-cell activation, which further restrains tumor progression." (PMID 34201127, 2021).